BIN1 (bridging integrator 1)
Diseases named in the same sentence as BIN1 in open-access papers (continued):
Sharing a sentence is not in itself a finding about the gene and the disease.
cognitive decline (13 papers, 2015 to 2025). "In other words, we propose that reduced inclusion of exon 7 into BIN1 proteins contributes to increases in tangle burden, which then causes more rapid cognitive decline." (PMID 32727516, 2020). "Our findings showed a strong association between BIN1 isoforms expressed by neurons/astrocytes and tangles that contributes to cognitive decline in AD, and our in situ studies refined these association to prioritize astrocytes as the target cell type." (PMID 32727516, 2020). "Experimental data have shown that the BIN1 SNP rs7561528 associates with entorhinal and temporal pole cortexes thickness, while the BIN1 rs744373 SNP correlates with the rate of cognitive decline and AD progression." (PMID 35994714, 2022). "Since the primary effect of BIN1 exon 7 on pathology may be exerted through tangles, we further explored whether this relation with tangles explained the association of BIN1 with cognitive decline." (PMID 32727516, 2020). "Since BIN1 genetic variants were previously associated with faster cognitive decline, we lastly test whether alterations in AV1451 tau-PET levels mediate the association between the BIN1 rs744373 SNP and worse memory performance." (PMID 30992433, 2019). "A variant in BIN1 (rs6733839) has been previously associated with AD risk and in this meta-analysis, a synonymous variant, rs61748155, located within BIN1 but not previously associated with AD risk, showed a suggestive P value for association with cognitive decline in AD (P = 3.2×10−5)." (PMID 39787209, 2025). "GWAS studies have repeatedly identified BIN1 as the second most significant susceptibility locus for LOAD after APOE, with multiple BIN1 SNPs associating with cognitive decline and impaired memory." (PMID 38368934, 2024). "Three isoforms of BIN1 were detected in neurons and astrocytes (isoforms 1, 2, and 3) and four isoforms in microglia (isoforms 6, 9, 10, and 12) of human brain showing a strong association of BIN1 isoforms expressed by neurons/astrocytes and tangles that might contribute to cognitive decline in AD." (PMID 35983068, 2022). "At present, the research on the role of BIN1 in AD is still in its infancy, which can understand the biological mechanism of cognitive decline and provide a new opportunity to find treatment sites." (PMID 35135506, 2022). "Genotyping of selected single-nucleotide polymorphisms in the APOE, ABCA7, SORL1, BIN1, GAB2, and CD33 genes was conducted, and a Bayesian hierarchical model was fitted to analyze the trajectories of cognitive decline among different genotypes." (PMID 34214049, 2021). "We evaluated the role of APOEε4 which has a strong role in AD, with both tangles and cognitive decline: specifically, APOEε4 explains approximately 7.7% of the variance in tangles while the BIN1 peptide LQAHLVAQTNLLR explains 2.8%." (PMID 32727516, 2020). "In addition, we report that exon 7 peptides of BIN1 are negatively correlated with tangles, suggesting that decreased expression of neuronal/astrocyte isoforms 1, 2, and 3 contributes to greater accumulation of tangles and cognitive decline." (PMID 32727516, 2020). "Decreased expression of BIN1 isoforms containing exon 7 is associated with greater accumulation of tangles and subsequent cognitive decline, with astrocytic rather than neuronal BIN1 being the more likely culprit." (PMID 32727516, 2020). "Up to now and not exclusive from each other, BIN1 polymorphisms have been associated with Tau but not amyloid loads in post-mortem AD brain tissue and they are consistently associated with faster Aβ-associated Tau-PET accumulation and cognitive decline in AD patient." (PMID 34998435, 2022). "To explore whether the BIN1 methylation in peripheral blood changed in the early stage of LOAD, we included 814 participants (484 cognitively normal participants [CN] and 330 participants with subjective cognitive decline [SCD]) from the Chinese Alzheimer’s Biomarker and LifestylE (CABLE) database." (PMID 33531457, 2021).
Parkinson disease (13 papers, 2019 to 2024). A progressive degenerative disorder of the central nervous system characterized by loss of dopamine producing neurons in the substantia nigra and the presence of Lewy bodies in the substantia nigra and locus coeruleus. "Mutations in BIN1 are thought to induce early-onset Parkinson disease in patients with at least one mutated GBA1 allele." (PMID 31464647, 2019). "Previous MR studies on Alzheimer’s disease suggest potential causal associations with BIN1, CCL27, C3, CD33, CD4 T cells, GDF-15 and SVEP1, whereas MR studies on Parkinson’s disease suggest a potential causal association with GPNMB, IL-6 and MIP1b." (PMID 37118290, 2022). "Variants in the BIN1 gene (p.Asn232Lys, and c.1462-3C > T) were linked to myopathy, while the variant in PTK2B was associated with Parkinson’s disease." (PMID 36133075, 2022). "There is evidence that the two main FEME components Endophilin and Bin1 are involved in neurodegeneration, in particular Alzheimer's and Parkinson's diseases." (PMID 32589750, 2020).
tauopathy (13 papers, 2014 to 2024). Neurodegenerative disorders involving deposition of abnormal tau protein isoforms (tau proteins) in neurons and glial cells in the brain. "In conclusion, we reveal the impact of overexpression of BIN1, a major genetic risk factor of AD, in a tauopathy model." (PMID 31065832, 2019). "However, there are opposite opinions that loss of forebrain BIN1 mitigates tau pathology in the hippocampus and entorhinal/piriform cortex of the tauopathy mice, thus attenuating synapse loss, neuronal death, neuroinflammation and brain atrophy." (PMID 38094504, 2023). "The G allele of the BIN1 gene is a potential risk factor for tauopathy." (PMID 32842621, 2020). "Interestingly, BIN1 has been described to be strongly expressed in oligodendrocytes and Tau has been also previously linked with potential myelin dysfunction in tauopathies." (PMID 31065832, 2019). "It is currently unclear whether BIN1 genetic variants are associated with tauopathies other than AD." (PMID 30992433, 2019). "Bridging integrator 1, whose role is implicated in tauopathy, is thought to interact with the CLU." (PMID 30134963, 2018). "Recent functional studies in the PS19 mouse model of tauopathy offer additional genetic support of a role for Bin1 in promoting tau-dependent AD." (PMID 37521457, 2023). "To this end we assessed for the first time the impact of human BIN1 overexpression in a mouse model of tauopathy and further dissected the interaction between Tau and BIN1 at the molecular and cellular levels." (PMID 31065832, 2019). "In this study, we aimed to determine if the BIN1–Tau interaction is involved in the neuropathological process of a mouse tauopathy model and to decipher the cellular processes and signaling pathways potentially regulating it." (PMID 31065832, 2019). "For the AD-associated gene BIN1, we confirm coordinated splicing, and we can now appreciate coordination in MAPT—a gene central to tauopathies." (PMID 29196558, 2018). "Moreover, human BIN1 overexpression in a mouse model of tauopathy has been shown to increase BIN1–Tau interaction in the neuronal network and to rescue long-term memory deficits and Tau somatic inclusions induced by human Tau overexpression." (PMID 30982098, 2019). "To determine if BIN1 could interfere with Tau pathology in vivo, we first developed a mammalian tauopathy model overexpressing BIN1 isoforms including neuron-specific forms in the brain." (PMID 31065832, 2019). "Although Bin1 mis-splicing has not been established in the DM brain, Bin1 is a recently identified genetic marker for predisposition to the most frequent tauopathy, AD." (PMID 24409116, 2014). "While preliminary, these findings encourage further research into the potential therapeutic benefits of this bioactive Bin1 MBD-targeting mAb to lower expression and deposition of phosphorylated tau, as a possible approach to treat AD and/or other tauopathies." (PMID 37521457, 2023). "Although a genetic interaction between Bin1 and MAPT has been shown in Drosophila and the corresponding proteins have been described to physically interact, the impact of BIN1 expression levels on cognitive function has not yet been investigated in a mammalian tauopathy model." (PMID 31065832, 2019). "Given evidence implicating Bin1 elevation in phosphorylated tau accumulation and neurofibrillary tangle pathology in AD, we explored whether administration of the Bin1 mAb 99D that produced a preclinical therapeutic benefit in IBD could produce any parallel benefits in model of tauopathy/AD." (PMID 37521457, 2023).
cardiomyopathy (12 papers, 2010 to 2023). A disease of the heart muscle or myocardium proper. "Complete deletion of Bin1 causes perinatal lethality due to cardiomyopathy, so its essential physiological and pathophysiological functions were probed in mosaic mice, where Bin1 was partly but not completely ablated throughout the animal." (PMID 37521457, 2023). "From a translational perspective, our discovery identifying PC1 as a positive modulator of BIN1 expression uncovers a novel mechanism implicated in ADPKD patient cardiomyopathy." (PMID 36614108, 2022). "In this study, BLITZ revealed several putative cavin interactors that have also been shown to be involved in cardiomyopathies and/or skeletal myopathies, including the membrane protein Dystrophin, the triad-associated proteins Bin1, Cypher/ZASP, and SPEG." (PMID 33591275, 2021). "The constitutive homozygous deletion of Bin1 is lethal in the first hours after birth and cardiomyopathy was proposed to be the fatal cause." (PMID 32994313, 2020). "Therefore, depletion of BIN1 at T-tubule membrane after knockdown could result in mislocalization of Cav1.2, causing inefficient excitation-contraction (EC) coupling and lethal cardiomyopathy." (PMID 20169111, 2010). "BIN1 knockdown also produces a cardiomyopathy, making this protein a potential mediator for TT remodeling during the development of HF." (PMID 35002765, 2021). "Father (III:4) and aunt (III:3) had the same variants in genes: ABCG8, BIN1, SCN2B, and SYNE1 (related to Emery-Dreifuss muscular dystrophy with cardiomyopathy, cardiac conduction defects, and cerebellar ataxia)." (PMID 33829027, 2021). "Aberrant myofibril organization in Bin1 knockout mice resulted in cardiomyopathy and embryonic lethality, emphasizing the importance of t-tubule structure in striated muscle." (PMID 21984944, 2011). "In conclusion, positive modulation of BIN1 expression by PC1 suggests a novel pathway that may be relevant to understanding the pathophysiological mechanisms leading to cardiomyopathy in ADPKD patients." (PMID 36614108, 2022). "Since BIN1 knockdown results in cardiomyopathy, it is possible that BIN1 may play a role in regulating the cardiac calcium transient." (PMID 20169111, 2010). "Several isoforms of the BIN1 protein are expressed with tissue and disease specificity and therefore some isoform BIN1 was discovered within cardiac transverse tubules (T-tubules) assumed to be important for cardiomyocyte homeostasis (calcium signaling) and is down-regulated in cardiomyopathy." (PMID 33829027, 2021). "Considering that ADPKD patients develop cardiomyopathy and that cardiospecific PC1-KO induces cardiac dysfunction in a mouse model, we focused on determining whether BIN1 expression and T-tubule formation are dependent on PC1." (PMID 36614108, 2022). "A previously published total Bin1 KO mice also died at birth, possibly from a suspected cardiomyopathy, with no reported defects of skeletal muscle structure." (PMID 32994313, 2020).
neuroblastoma (11 papers, 2011 to 2025). Neuroblastoma (NB) is the most common solid, extracranial childhood tumor. "Interestingly, the variant rs59335482, an insertion allele associated with a higher AD risk, is able to increase transcriptional activity in a luciferase assay in vitro using HEK cells and SH-SY5Y neuroblastoma cells, and is also associated with an increase in BIN1 mRNA expression in the brain." (PMID 34998435, 2022). "BIN1 was found to co-immunoprecipitate with Tau following overexpression of both proteins in SY5Y neuroblastoma cells, and an interaction between endogenous BIN1 and Tau was also demonstrated to occur in synaptosomes from mouse brain." (PMID 25051234, 2014). "BIN1 can also interact with cytoplasmic linker protein CLIP-170; studies found an interaction between tau protein and BIN1 in human neuroblastoma cell." (PMID 31366155, 2019). "BIN1 expression is reduced or absent in many human cancers, including esophageal, gastric, neuroblastoma, breast, lung, colorectal, prostate, pancreatic cancers, and malignant pleural mesothelioma., making it an important focus in cancer research." (PMID 40016843, 2025). "Neither knocking down endogenous BIN1 expression with targeted siRNA nor overexpression of BIN1 in a human neuroblastoma cell line had an effect on APP processing." (PMID 24205320, 2013).
myotonic dystrophy (10 papers, 2013 to 2024). An inherited progressive disorder affecting the muscles. "Given that dysregulated splicing of BIN1 is associated with muscle weakness in myotonic dystrophy (DM), we directed our focus toward Bin1 variants for further analysis." (PMID 39248331, 2024). "Dysregulated alternative splicing of BIN1 has been linked to T-tubule alterations and muscle weakness in myotonic dystrophy." (PMID 39248331, 2024). "Of the 50 muscle-relevant, statistically significant alternative splicing aberrations in the ST-3500 myoblast cultures, one mis-splicing event in BIN1 (exon 11) associates with T tubule alterations and muscle weakness in myotonic dystrophy." (PMID 25211016, 2014). "Mis-splicing of amphiphysin-2/BIN1 is also associated with myotonic dystrophy that shares histopathological hallmarks with CNM." (PMID 25262827, 2014). "Mis-splicing of the BIN1 muscle-specific exon 11 was reported in different forms of myotonic dystrophy (DM)." (PMID 23754947, 2013). "In addition, Bin1 splicing defects in the exon responsible for the interaction of Bin1 with membrane phosphoinositides induce T-tubule defects in myotonic dystrophy." (PMID 37083699, 2023). "In addition, misregulation of BIN1 splicing partially accounts for the muscle defects in myotonic dystrophy (DM)." (PMID 23754947, 2013). "Alternative splicing of BIN1 exon 11 is mis-regulated in patients with myotonic dystrophy." (PMID 23754947, 2013). "Our data therefore support the hypothesis that mis-splicing of BIN1 exon 11 partially accounts for the muscle-specific signs in myotonic dystrophy." (PMID 23754947, 2013).
mild cognitive impairment (9 papers, 2017 to 2025). "For these reasons, and it is imperative to reproduce and validate these results in other cohorts with larger populations and investigate the possible association of other BIN1 polymorphisms with cognitive deficits." (PMID 39081475, 2022). "Future studies in the Portuguese population should evaluate other BIN1 variants in the context of cognitive deficits." (PMID 39081475, 2022). "Regarding BIN1, in the pcb-Cohort the G risk allele of rs744373 SNP does not seem to be associated with either socio-demographic characteristics or cognitive deficits." (PMID 39081475, 2022). "This suggests that BIN1 rs744373 contributes to the development of tau pathology in at-risk subjects, resulting in stronger cognitive impairment." (PMID 30992433, 2019). "The current findings suggest that tau pathology provides a key link that underlies the association between BIN1 genetic variants and cognitive impairment." (PMID 30992433, 2019). "Additionally, a study showed an association between BIN1 rs744373 and high levels of total tau and tau protein phosphorylated at threonine 181, measured in CSF samples of mild cognitive impairment (MCI) and AD patients." (PMID 39081475, 2022). "Likewise, the relevance of the rs744373 variant of BIN1 as a potential risk factor associated with cognitive deficits in this Portuguese population was investigated." (PMID 39081475, 2022). "A key hypothesis for the role of BIN1 in AD is the aggravation of tau pathology, i.e. a key primary brain pathology associated with cognitive impairment in AD14,15." (PMID 30992433, 2019). "In particular, preventing or reversing the dysregulation of key OL driver genes such as CNP and downstream targets such as BIN1 deserve further research as interventions to help to alleviate the progression of cognitive deficits in AD." (PMID 29110684, 2017). "In the parallel statistical analysis none of the BIN1 rs744373 genotypes were associated with age at diagnosis, disease duration, or scores on cognitive deficit assessment scales." (PMID 41465142, 2025). "Our findings represent an important contribution to the understanding of the role of BIN1 in AD, as we demonstrate in living non-demented elderly subjects an association of BIN1 rs744373 and regional elevation of tau pathology, i.e., a key AD pathology associated with cognitive impairment." (PMID 30992433, 2019). "This study was the first to systematically explore the associations of methylation of BIN1 promoter in peripheral blood with preclinical AD susceptibility and early pathological changes of CSF AD core biomarkers in a large cohort of participants without objective cognitive impairment." (PMID 33531457, 2021). "The main finding of our study was that hypomethylation of BIN1 promoter might increase the risk of preclinical AD and be associated with more severe pathological changes of CSF AD core biomarkers in elderly adults without objective cognitive impairment." (PMID 33531457, 2021). "Although SNPs from BIN1 (rs744373) loci may not play a major role in PD, PD dementia (PDD), or PD-mild cognitive impairment in a Chinese population, SNPs from BIN1 (rs6733839) loci was identified in patients with Lewy body diseases (LBDs) in a Caucasian population." (PMID 32842621, 2020).